KRT87P (keratin 87, pseudogene)
Synonyms: KRT121P; KRTHBP4; psihHbD
Target class: Structural protein
Gene: Transcribed unprocessed pseudogene on chromosome 12 (52,250,466 to 52,258,553, reverse strand). Ensembl gene ENSG00000135477.